AURKA (aurora kinase A)
Diseases named in the same sentence as AURKA in open-access papers (continued):
Sharing a sentence is not in itself a finding about the gene and the disease.
cancer (continued). "The alteration frequency of AURKA correlated with caspase 3, 7, and 8 in the TCGA Pan-Cancer Atlas study." (PMID 38994036, 2024). "In summary, the Asp132-cleavage of AURKA can be induced in various human cancer cells by Taxol in a caspase 3/7/8-dependent manner, and the Asp132-cleavage products cause centrosome and spindle assembly defects during mitosis to induce cell apoptosis." (PMID 38994036, 2024). "HMMR’s association with key cell cycle regulators (AURKA, TPX2, and CDK1) underscores its pivotal role in cancer initiation and advancement." (PMID 38576486, 2024). "Beyond cancer, AURKA emerges as a multifaceted player in host cell modulation, exerting influence over inflammatory responses, cell death mechanisms, and autophagy pathways." (PMID 41907711, 2024). "Following the analysis of publicly available data from TCGA, it was clear that AURKA overexpression at the level of the mRNA is prevalent in many cancers, a finding previously reported." (PMID 39527514, 2024). "While the oncogenic potential of AurkA has been proposed since its first identification in human cells, the link between AurkB and cancer was initially less explored." (PMID 39195284, 2024). "AURKA promotes tumorigenesis by participating in epithelial‐mesenchymal transformation, proliferation and metastasis of cancer cells, apoptosis, and self‐renewal of stem cells." (PMID 39118481, 2024). "This article describes an exploratory analysis around the expression of AURKA on a pan-cancer scale." (PMID 39527514, 2024). "The regulatory network involving ncRNAs and AURKA is a promising source of diagnostic and prognostic biomarkers in HCC and other cancers." (PMID 39598228, 2024). "AURKA's critical involvement in modulating cellular pathways and its overexpression in cancer makes it an attractive target for anticancer therapies." (PMID 38590119, 2024). "Subsequently, the correlation between AURKA mRNA and hsa-let-7a expression levels (‘mRNA vs hsa-let-7a’) in individual cancer samples was interrogated as a route to infer the role of hsa-let-7a in modulating AURKA expression." (PMID 39527514, 2024). "The intricate interplay between ncRNAs and AURKA in HCC offers profound clinical implications, shaping diagnostic, prognostic, and therapeutic paradigms in cancer management." (PMID 39598228, 2024). "The pan-cancer analysis of AURKA mRNA expression revealed a general trend of increased mRNA levels in cancer tissues, although to varying extents." (PMID 39527514, 2024). "Overexpressing AurkA in nontransformed murine cells, either immortalised cell lines or MEFs from transgenic mice, led to 10–20% of cells having >2 γ-tubulin foci, and higher occurrence was observed after AurkA overexpression in human cancer cell lines." (PMID 39195284, 2024). "Collectively, our data suggest that downregulation of AURKA in KRASG12C inhibitor–treated cancer cells induces Hh signaling and re-expression of KRAS." (PMID 38225225, 2024). "When we analyzed the expression level of AURKA in cancer cells, we found that the KRASG12C inhibitor ARS-1620 decreased both mRNA and protein levels of AURKA in H23 and H358 cells at 24 h post-treatment but increased them slightly at 72 h post-treatment." (PMID 38225225, 2024). "Given the higher translation rate of the short APA isoform, APA likely contributes to the increased expression of AURKA in cancers." (PMID 39527514, 2024). "AURKA demonstrates considerably elevated levels of expression in various cancer tissues compared to normal control tissues." (PMID 38633613, 2024). "We demonstrate for the first time that AURKA, a key serine/threonine kinase in mitosis, undergoes proteolytic cleavage at Asp132 in various cancer cells in response to apoptotic stimuli." (PMID 38994036, 2024). "Here, using the APAtrap software to interrogate our curated TCGA samples, AURKA SLR was discovered to have increased in almost all cancers compared to their normal tissues." (PMID 39527514, 2024).
cancer (continued). "Four key genes CCL2, CCR7, LY96, and PTPRC, from ClusterK1 and five genes AURKA, CDK1, CCNA2, FEN1, and PLK1 from ClusterK2, were associated with at least one type of cancer." (PMID 38872418, 2024). "AURKA also plays additional cancer-promoting roles in cell proliferation, survival, migration, and cancer stem cell phenotypes, some of which in interphase and in a kinase-independent manner." (PMID 37384380, 2023). "The positive effects of AURKA on endothelial cell function and angiogenesis have been established in cancer." (PMID 36977984, 2023). "Our analysis revealed that AURKA is prominently overexpressed in a majority of the cancer types under investigation." (PMID 37965456, 2023). "On the contrary, AURKA shows significantly higher expression in cancer tissues than in normal control tissues for multiple malignancies according to the TCGA database." (PMID 37521469, 2023). "Together, our results suggest that AURKA/TPX2 co-overexpression in cancer has an impact not only on mitotic but also on interphasic nuclear AurkA oncogenic functions." (PMID 36797043, 2023). "Several studies reported that some AURKA substrates, including GSK3β and β-catenin, participated in crucial oncogenic signaling, and AURKA directly phosphorylated GSK3β in cancer cells, which stabilized β-catenin and activated Wnt signaling." (PMID 36937887, 2023). "Given its critical role in cell division and cancer, there has been great interest in developing inhibitors targeting AURKA over the last two decades." (PMID 36830089, 2023). "To gain a deeper understanding of the relationship between AURKA and tumor immunity, we investigated the association between AURKA expression and both ESTIMATE and immune scores in various human cancers." (PMID 37965456, 2023). "Most investigations have consistently demonstrated high AURKA expression in the majority of cancers, affecting tumor proliferation and invasion capabilities." (PMID 37965456, 2023). "AURKA is a serine/threonine kinase with crucial functions in mitosis and has aberrant expression in most cancer types." (PMID 37894278, 2023). "AURKA shows significantly higher expression in cancer tissues than in normal tissues for multiple tumor types including HCC." (PMID 37773181, 2023). "Amplification of the chromosomal region 20q13 where the AURKA gene is located is commonly observed in cancer cells." (PMID 36839989, 2023). "Aurora kinase A (AURKA) and Aurora kinase B (AURKA), which their overexpression is highly related to cancer emergence, have been found to play a crucial role in cell proliferation and division." (PMID 37231064, 2023). "Our findings strongly support the utility of AURKA as a prognostic marker across various cancer types." (PMID 37965456, 2023). "Few miRNAs have been pointed to as regulators of AURKA mRNA but, importantly, reported cases of miRNA targeting of AURKA occur in those cancers where AURKA overexpression is a promoting factor or a marker of poor prognosis." (PMID 37384380, 2023). "In summary, our investigation comprehensively analyzed AURKA’s oncogenic role and prognostic significance across diverse cancer types, shedding light on its overexpression and potential clinical relevance, especially in EAC." (PMID 37965456, 2023). "To validate the robustness of AURKA expression and its prognostic value, we analyzed pan-cancer data from GEO cohorts." (PMID 37965456, 2023). "The involvement of all of these crucial cancer-related pathways revealed the fundamental role of AURKA in tumorigenesis and progression." (PMID 36750558, 2023). "Alisertib is an AURKA inhibitor used in several clinical trials for many types of cancers, in particular hematopoietic tumors." (PMID 36899930, 2023).
cancer (continued). "In our current study, we scrutinized AURKA expression levels across 27 types of human cancer, revealing up-regulation in 26 cancer types and down-regulation in just one (LAML)." (PMID 37965456, 2023). "In this respect, it is interesting to note that ubiquitin ligases that modulate AurkA stability, for example, Fbxw7 and VHL, are frequently mutated in cancer (references 22, 50 and references therein)." (PMID 36797043, 2023). "Aberrant expression of AURKA has been observed in various human cancers, spanning gastric, esophageal, colon, ovarian, and pancreatic cancers." (PMID 37965456, 2023). "Our work paves the way to novel anti-cancer therapies targeting the AURKA/ATP5F1A/ATP5F1B nexus to lower cancer cell metabolism and proliferation." (PMID 37386025, 2023). "Our study elucidates the oncogenic role of AURKA and underscores its prognostic value across a spectrum of cancers, including EAC." (PMID 37965456, 2023). "Amplification of AURKA has been validated in various cancer types, including ovarian, gastric, and bladder cancer, and proposed to be an oncogene." (PMID 36977984, 2023). "We conducted a comprehensive analysis by combining normal samples from the GTEx dataset with tumor samples from the TCGA dataset to investigate the differential expression of AURKA across 27 different human cancer types." (PMID 37965456, 2023). "Currently, targeting MYCN through inhibiting bromodomain-containing proteins and Aurora Kinase A in various cancers is well studied." (PMID 37543638, 2023). "Our findings expand our understanding of the AURKA degradation pathway, and provides a new theoretical basis for the cancer therapy targeting AURKA, but more studies are needed on how TIALD directs its targeting to lysosomes by binding to AURKA." (PMID 37773181, 2023). "The TCGA database also states that high expression of AURKA is a prognostic marker in several cancers." (PMID 36937887, 2023). "KIF11 and AURKA are overexpressed in many different cancer types, indicating the importance of this mitotic machinery to facilitate aggressive tumor growth." (PMID 37894278, 2023). "Prognostic value analysis revealed that increased AURKA expression correlated with poorer outcomes in most cancers, aligning with previous studies." (PMID 37965456, 2023). "AURKA induces the progression of tumors by participating in cancer cell metastasis, apoptosis, growth, epithelial-mesenchymal transition, and the self-renewal of cancer stem cells." (PMID 36937887, 2023). "Aurora kinase A (AURKA) has become a crucial participant in facilitating tumor generation and cancer development." (PMID 37415951, 2023). "AURKA (Aurora-A) is a member of Aurora kinase family involved in the regulation of mitosis, and is reported to be over-expressed in many human cancers including HCC." (PMID 37773181, 2023). "Aurora Kinase A (AURKA) is an oncogenic kinase with major roles in mitosis, but also exerts cell cycle- and kinase-independent functions linked to cancer." (PMID 37384380, 2023). "Our results suggest therefore that in certain cancer types, AURKA overexpression correlates with increased import rates." (PMID 36797043, 2023). "We conducted a comprehensive analysis of AURKA expression in various cancers using data from The Cancer Genome Atlas, Genotype-Tissue Expression, and The Human Protein Atlas databases." (PMID 37965456, 2023). "This further confirms that the oncogenic effect of AURKA, reinforcing the widespread oncogenic influence of AURKA and its potential as a therapeutic target in future cancer treatment." (PMID 37965456, 2023). "Several studies emphasize the significance of AURKA in cancer treatment after extensive research into its functions." (PMID 38113210, 2023). "Due to the cogent effect of AURKA in various cancers, different inhibitors are designed and tested to halt cancer progress by suppressing this gene’s upregulation." (PMID 37231064, 2023).
cancer (continued). "Emerging evidence proposes that this AurkA fraction operates through both kinase-dependent and kinase-independent roles in cell transformation and cancer, highlighting the importance to better understand its regulation." (PMID 36797043, 2023). "Activation of AURKA has been shown to have an important role in a broad range of cancers, and its inhibitors have been subjected to clinical trials as monotherapies or in combination with classic chemotherapy or other targeted therapies." (PMID 36778123, 2023). "Retrieving the immune-TME and TNBC aggression-associated marker genes from the Pan-cancer TCGA-dataset, we found a high positive correlation of the expression of S100A9 and S100A8, two immune suppression marker genes, with AURKA and EZH2 in the TNBC samples." (PMID 37189841, 2023). "To establish the prognostic significance of AURKA, we employed KM and univariate Cox regression analyses using the TCGA pan-cancer data." (PMID 37965456, 2023). "AURKA overexpression is frequently observed in many cancer types and targeting the kinase is studied as an anti-cancer therapeutic approach." (PMID 36797043, 2023). "Having established that APA plays a role in regulating AURKA expression, we tested the idea that AURKA APA directly contributes to cancer cell behavior by performing genome editing to alter AURKA APA in wild-type U2OS cells." (PMID 37384380, 2023). "A comprehensive analysis of AURKA’s oncogenic role and prognostic relevance across various cancer types, highlighting its overexpression and clinical significance in diverse malignancies." (PMID 37965456, 2023). "AURKA functions as an oncogene by regulating multiple molecular targets that involved in the regulation of cancer proliferation, apoptosis, metastasis, genomic instability and stemness." (PMID 37773181, 2023). "We propose that AURKA/TPX2 co-overexpression in cancer represents a key determinant of AurkA nuclear oncogenic functions." (PMID 36797043, 2023). "The AURKA expression was significantly increased in carcinomas compared with normal proliferative endometrium." (PMID 37286702, 2023). "We and others have demonstrated that AURKA promotes cancer progression in a kinase-dependent manner." (PMID 36471438, 2022). "As a result, we investigated the relationship of AURKA with immunological checkpoints, DNA repair genes, and methyltransferases in pan-cancer." (PMID 36685952, 2022). "In recent years, growing evidence uncovered novel cancer-promoting roles of AURKA that are kinase-independent and occur in the nucleus." (PMID 36067794, 2022). "Most notably, studies have explored the biological function of AURKA in human cancers, such as diffuse large B-cell lymphoma, glioblastoma, gastric, cervical, colorectal, and liver cancers." (PMID 36072667, 2022). "Abnormal activity of AURKA promotes tumorigenic progression and is highly expressed in various cancers, including HCC." (PMID 36557005, 2022). "One of the most significant genes was AURKA, a cell cycle protein that is also overexpressed in cervical and ovarian cancers and seems to be key in the pathogenesis of LMS since its inhibition results in cell cycle arrest and apoptosis in LMS cell lines." (PMID 35216305, 2022). "Through qRT-PCR, the expression of AURKA was found to be significantly higher in cancer tissues compared to normal tissues (Wilcoxon rank-sum test, p < 0.05)." (PMID 36072667, 2022). "AURKA was shown to be favorably connected with the indication of immune checkpoint genes, which supports our prior results from a pan-cancer immunological correlation study." (PMID 36685952, 2022). "Since an overexpression and gene amplification of AURKA have been found in various cancers, small-molecule AURKA kinase inhibitors are of great interest." (PMID 36291769, 2022).
cancer (continued). "We and others have shown that AURKA plays vital biological functions to promote cancer cell survival." (PMID 35326553, 2022). "Particularly, AURKA, as a classical oncogene, has been widely studied regarding the proliferation of cancer cells." (PMID 35875069, 2022). "“Proliferative CAFs” in Branch 5 specifically expressed PRC1, a mitotic spindle-associated protein, and Aurora A kinase (encoded by AURKA), both of which are known to promote cancer cell proliferation and tumor growth." (PMID 35884546, 2022). "AURKA was significantly positively correlated with Th2 cells in all 40 cancers studied, and it was the first positive correlation." (PMID 36685952, 2022). "Overall, the discovery of AURKA nuclear translocation inhibitors provides a novel therapeutic route for future cancer treatment." (PMID 35361747, 2022). "AURKA is a member of the serine/threonine kinase family, which has been shown to act as an oncogene, promoting carcinogenesis in a variety of cancer types, including solid tumors and haematological malignancies." (PMID 36408344, 2022). "Immunohistochemistry (IHC) staining showed that AURKA was highly accumulated in the nuclei of cancer tissues compared to adjacent tissues." (PMID 35361747, 2022). "Aurora Kinase A (AKA) inhibition with gemcitabine represents a potentially synergistic cancer treatment strategy via mitotic catastrophe." (PMID 35907014, 2022). "Addressing the open questions highlighted in this review will be crucial to discern which stage of gene expression would be more efficient to target when the aim is to correct AURKA abundance in cancers where it is altered." (PMID 36067794, 2022). "Ectopic expression of AURKA induces oncogenic transformation in mouse and rat fibroblasts and is suggested to be a potential therapeutic target against different cancers." (PMID 35378133, 2022). "In our previous study, we developed a series of quinazolin-4(3H)-one inhibitors for aurora kinase A that exhibit antiproliferative activity against cancer cells." (PMID 35745617, 2022). "Our results are in accordance with those of studies showing that AURKA displays a kinase-independent function to promote cancer progression." (PMID 36471438, 2022). "The abnormal expression of Plk1 and AURKA is proven to be toughly related to the tumorigenesis of many cancer types." (PMID 35656338, 2022). "Cancer growth can also be reliant on high expression of specific E2 cell cycle target genes including AURKA, KIF4A, STAG1, CTCF, and RPA1, all of which were identified highly expressed in at least one of the at-risk samples studied here." (PMID 35459280, 2022). "In summary, knockdown of tRF-Leu-CAG by tRF-Leu-CAG inhibitor can repress AURKA, suppressing cancer cell proliferation and impeding cell cycle at last." (PMID 36072340, 2022). "We then investigated AURKA expression in pan-cancer, and the results show that AURKA was highly expressed in all 31 tumors except PCPG and THCA." (PMID 36685952, 2022). "AURKA has been shown to be highly expressed in certain malignant tumors and is potentially involved in the prophase of mitosis to promote G2/M transition." (PMID 36072667, 2022). "All of these data points to AURKA as a potential target for cancer treatment, and various small compounds targeting AURKA have been found." (PMID 35574421, 2022). "The combined treatment using AURKA inhibitor and tunicamycin synergistically induced cancer cell death." (PMID 35326553, 2022). "Quantitatively and qualitatively aberrant AURKA expression in patients with different cancers have been observed at all levels of gene expression." (PMID 36067794, 2022). "AURKA-mediated phosphorylation can regulate the function of AURKA-discovered substrates, some of which are filamentous regulators, tumor suppressors, or factors in cancer." (PMID 36713509, 2022). "Further studies are warranted to explore new mechanisms of AURKA in cancer development and develop novel small molecular inhibitors of AURKA." (PMID 36471438, 2022).